SST (somatostatin)
Diseases named in the same sentence as SST in open-access papers (continued):
Sharing a sentence is not in itself a finding about the gene and the disease.
insulinomas (16 papers, 1986 to 2025). "It is estimated that about 70% of insulinoma tumors present receptors for somatostatin, which inhibit pancreatic extra- and endocrine function, thus contributing to a reduction in the severity of clinical symptoms." (PMID 40565772, 2025). "Somatostatin expression in EndoC-βH1 cells has been noted previously and is observed in insulinomas." (PMID 35378291, 2022). "The immunoreactive glucagon and somatostatin contents of extrapancreatic tissues of insulinoma-bearing rats were unchanged." (PMID 2877684, 1986). "Consistent with previous reports, miR-204 expression was enriched in insulinomas and drastically lower in both non-functional PETs and functional PETs expressing glucagon or somatostatin." (PMID 29070792, 2017). "The expression of ATP6AP2 proteins was clearly detected in insulin-expressing cells of normal islets near the insulinoma lesions and nonfunctioning NETs, whereas it was not or faintly detected in glucagon-expressing cells and somatostatin-expressing cells in the same regions." (PMID 37286698, 2023). "Among 24 islet 1-positive PanNETs investigated (11 G1 and 13 G2 tumors), scattered cytoplasmatic RSUME immunopositivity was observed in insulinomas (n = 7) whereas RSUME was absent in the vast majority of the other PanNETs including 4 somatostatin expressing tumors." (PMID 27506944, 2016).
pancreatic cancer (16 papers, 1992 to 2025). "Our study is aimed at exploring the cause from different therapeutic effects of somatostatin and its analogs on human pancreatic cancer and their relationship between changes of SSTR-2 gene expression and expression of SSTR-2, SSTR-3, and SSTR-5 genes." (PMID 25890201, 2015). "Our results show that SST gene hypermethylation and simultaneous downregulation of expression occurs in pancreatic cancer and a broad range of other tumor entities, acting as a pan‐cancer molecular biomarker." (PMID 32243066, 2020). "In order to learn how specific the variations in SST methylation and expression are to pancreatic cancer, we took advantage of TCGA expression and methylation data for an analysis of other gastrointestinal cancers." (PMID 32243066, 2020). "Using genomewide DNA methylation experiments, we showed that the SST gene is hypermethylated in pancreatic tumors." (PMID 32243066, 2020). "Several studies have demonstrated the decrease in cell proliferation induced by SST and SST analogs in SSTR2-positive pancreatic cancer cells." (PMID 29700299, 2018). "Using the publicly available data sets from the Human Protein Atlas Program, we confirmed that SST protein is expressed in normal pancreatic tissues, but strongly repressed in pancreatic tumors." (PMID 29700299, 2018). "Based on information that receptors for somatostatin and bombesin are expressed in pancreatic cancers we tested the effects of cytotoxic analogs of somatostatin (AN-238) and bombesin (AN-215) on human pancreatic cancer lines xenografted into nude mice." (PMID 23744510, 2013). "As SST is known to be secreted by pancreatic cells, it may have been used as a cell attractant for the spheroids generated from the pancreatic cancer cell line in our experiment." (PMID 39554905, 2024). "In addition, PTPN6 has been reported to control cell proliferation and determine the therapeutic potential of somatostatin in pancreatic cancer." (PMID 34654352, 2021). "Moreover, a Pearson’s correlation of the SST methylation profile with expression levels using methylation and expression data of pancreatic cancer in TCGA‐PAAD found a significant inverse correlation (r = −0.4161, P < 0.0001)." (PMID 32243066, 2020). "Moreover, for validation of SST downregulation, we used expression data from other, independent cohorts of pancreatic cancer available in GEO." (PMID 32243066, 2020). "Our working hypothesis was that such fibro-inhibitory role of somatostatin may alter the pro-tumor activity of CAFs present in cancers where a desmoplasic reaction is prominent, including pancreatic cancer." (PMID 27177087, 2016). "In previous studies, various other of our cytotoxic conjugates, such as cytotoxic analog of LH-RH (AN-207), somatostatin (AN-238) and bombesin (AN-215), powerfully inhibited growth in nude mice of human pancreatic cancer lines that expressed the specific receptors for those carrier peptides." (PMID 23744510, 2013). "In addition, we explored the molecular mechanism underlying the reversion of the epigenetic silencing of characteristic markers expressed the pancreas, in particular for the antiproliferative hormone somatostatin (SST), which was seen in reprogrammed pancreatic cancer cells." (PMID 29700299, 2018). "Furthermore, down-regulated mRNAs of the kallikrein peptidase family (Klk1, Klk1b3, Klk1b5) and the cholecystokinin receptor type A (CCKAR), and expression of cdh2 coding for N-cadherin as well as somatostatin discriminated pancreatic tumors from pancreatic controls." (PMID 27769070, 2016). "Therefore, before implementing therapy by long-acting somatostatin analogs such as octreotide in pancreatic cancer patients, to make sure that tumor tissue have high affinity somatostatin receptors, it is important to improve efficacy and reduce unnecessary costs." (PMID 25890201, 2015). "In addition, it was found that somatostatin and its analogs could arrest the pancreatic cancer cell cycle at S phase and thus induce apoptosis." (PMID 25890201, 2015).
pancreatic cancer (continued). "We also found that the somatostatin agonist octreotide has antiproliferative and antimigratory effects on PDAC cell lines, providing more evidence on its tumor suppressive roles in pancreatic cancer." (PMID 32243066, 2020). "In the present work, we reported that an epigenetic therapy regimen using the demethylating agent 5-AZA significantly inhibited pancreatic tumor growth and sensitized the PDAC cell line PANC-1 to GEM and SST analog treatment." (PMID 29700299, 2018). "Because the current study shows that the ability of somatostatin to inhibit tumor cell growth is mediated by SSTR-2, it is very important for patients suffering from pancreatic cancer to receive somatostatin treatment." (PMID 25890201, 2015). "The system consisted of liposomes as carriers, an anticancer drug (paclitaxel) as a chemotherapeutic agent, and a modified synthetic somatostatin analog, 5-pentacarbonyl-octreotide, a ligand for somatostatin receptor 2 (SSTR2), as a targeting moiety for pancreatic cancer." (PMID 38791582, 2024). "From our tissue data, one would expect that SST methylation will not be usable as a marker of pancreatic cancer in particular." (PMID 32243066, 2020). "In vitro data also demonstrated absence of SSTR2 expression, suggesting pancreatic cancer not to be a potential target for treatment with SST analogues." (PMID 10027326, 1999). "Cell-free DNA hypermethylation of BMP3, MESTv2, SST, TFPI2, TAC1, ALX4, HIC1, SFRP2, SEPT9v2 and WNT5A has not previously been described in the literature in relation to pancreatic cancer." (PMID 27891190, 2016). "In experimental pancreatic tumor, the growth of both functioning pancreatic tumors and nonfunctioning tumors with SSTR-2 gene expression is inhibited by somatostatin, while there is no inhibitory effect on non-SSTR-2 gene expression cells." (PMID 25890201, 2015). "Strikingly, CAF treatment with a novel pan-somatostatin analog SOM230 (Pasireotide® Novartis) does not directly affect their survival, nor the survival of pancreatic cancer cells whether or not they are also exposed to CAF CM (bars 4 & 5)." (PMID 27177087, 2016).
prostate carcinoma (16 papers, 2005 to 2024). A carcinoma that arises from epithelial cells of the prostate gland. "SSTR2 deficiency in prostate cancer may explain the treatment ineffectiveness of some selective somatostatin analogs." (PMID 33586406, 2021). "Certain components of the somatostatin-system play relevant roles in Prostate Cancer (PCa), whose most aggressive phenotype (Castration-Resistant-PCa (CRPC)) remains lethal nowadays." (PMID 32498336, 2020). "SSTR2, a G-protein coupled receptor for somatostatin is an inhibitory hormone produced by immune and neuroendocrine cells It is also expressed in several types of cancers, including prostate cancer and leukemia." (PMID 26461935, 2015). "Cell growth inhibition was detected in colorectal, gastric, pancreatic, breast, cervical, lung and prostatic cancer cell lines following administration of SST analogues." (PMID 25723531, 2015). "Many studies using SST analogs (octreotide, lanreotide, pasireotide) have been performed in prostate cancer cell lines highlighting both antiproliferative and proapoptotic effects." (PMID 23476673, 2013). "It is interesting to evaluate the potential regulatory effects of somatostatin on XAF1 expression during the development of prostate cancer cells." (PMID 21143993, 2010). "In prostate carcinoma, the androgen deprivation can also lead to development of a negative growth-regulating loop involving antiproliferative peptides like somatostatin." (PMID 19365586, 2009). "In this context, it is interesting to note that PTGS1 methylation is frequent in prostate cancer, THY1 has been implicated as a candidate TSG in nasopharyngeal cancer and SST promoter methylation has been described in ∼90% of colorectal cancers." (PMID 18195710, 2008). "Interestingly, some existing studies also support SST and its analogs’ role in combination with Docetaxel and metastatic castrate-resistant prostate cancer." (PMID 38203605, 2023). "Moreover, blocking endogenous SST supports the antiproliferation effect of prostate cancer in an SHP-1-dependent manner." (PMID 38203605, 2023). "Similarly, the use of SST analogs conjugated with doxorubicin (AN-162) showed a powerful in vitro and in vivo efficacy in experimental prostate cancer model, being also able to affect metastasization." (PMID 23476673, 2013). "The effects of somatostatin on the prostate cancer cells may be mediated by enhanced expression of XAF1 through its pro-apoptotic effect." (PMID 21143993, 2010). "Treatment with somatostatin may therefore be a possible therapeutic alternative to chemotherapy in hormone refractory prostate cancer patients." (PMID 21143993, 2010). "In the case of SST, its synthetic analogs (e.g., octreotide and lanreotide) have been shown to inhibit the proliferation of several tumor-derived cell lines in vitro, and to reduce tumor progression in vivo in studies using preclinical models of breast and prostate cancer." (PMID 26956474, 2016). "We found that somatostatin and Octreotide up-regulated XAF1 mRNA and protein expression in prostate cancer cell lines." (PMID 21143993, 2010). "So far, in clinical trials, only non-radiolabelled SST or its analogues are used to treat prostate cancer that also without any major success." (PMID 38203605, 2023). "Other examples include arbutin (hydroquinone-O-beta-d-glucopyranoside), a tyrosinase inhibitor in A375 human malignant melanoma cells, and somatostatin, used in the treatment of advanced prostate cancer, which upregulated the expression of VDAC1 and VDAC2 in the LNCaP prostate cancer cell line." (PMID 28824871, 2017). "Of particular interest are: FGF9 which may stimulate the growth of prostate cancer, brain cancer and endometrium; and IER3 (IEX-1), PHLDA2 (TSS3), IAPP (amylin), and SST, all of which may play roles in apoptosis." (PMID 15691381, 2005).
prostate carcinoma (continued). "Our previous results have shown that somatostatin may affect the mitochondria of LNCaP and DU145 cells in a way that eventually triggers mitochondrial-mediated apoptosis and exert its effects on prostate cancer cells via MAPK pathway and by regulating the activities of phosphotyrosine phosphatases." (PMID 21143993, 2010).
carcinoids (15 papers, 1988 to 2025). "Octreoscan is the first approved radiopharmaceutical for carcinoid tumor imaging; it consists of somatostatin analogs radio-labelled with 111 Indium, used to detect somatostatin receptor positive tissue." (PMID 33923121, 2021). "We have shown that in our NET model system SST analogue treatment primarily induces changes in miRNA expression profiles in carcinoid cell lines." (PMID 29973528, 2018). "Here we show that SST analogues inhibit the growth of two carcinoid cell lines and that the inhibitory potential depends on the analogue used." (PMID 29973528, 2018). "Primary carcinoid tumors as well as metastasis possess high affinity receptors for somatostatin in 87% of cases." (PMID 24741994, 2014). "Primary carcinoids and metastatic lesions do have high affinity receptors for somatostatin in 87% of cases." (PMID 23997766, 2013). "This is in good concordance with other studies that also show that SST analogues inhibit the growth of the NCI-H727 carcinoid cell line and the CNDT2 carcinoid cell line and that a chimeric compound targeting SSTRs and DRD2s has the most potent growth inhibitory effect." (PMID 29973528, 2018). "The extent to which carcinoid tumors are regulated by other hormones is not clear; however, they do express receptors for IGF-1, somatostatin, and gastrin overproduction was linked to the development of at least a subtype of carcinoid tumors." (PMID 26290759, 2015). "In the future, novel somatostatin analogues with subtype specific receptor profiles may prove to be of value for individualizing the treatment of disseminated carcinoid tumour disease." (PMID 9484822, 1998). "Interestingly, some of the peptidergic genes expressed in only minor subpopulations of normal PNECs (e.g. NPW, NPPA, SST, CARTPT) were detected in many carcinoids, whereas the nearly ubiquitous PNEC peptidergic gene CALCA was absent from most carcinoids." (PMID 36469459, 2022). "The presence of a number of regulatory peptides (bombesin, gastrin, glucagon, somatostatin, calcitonin and ACTH) was compared in 30 typical carcinoid tumours and 27 well differentiated neuroendocrine carcinomas (atypical carcinoids) using conventional immunocytochemistry." (PMID 2906252, 1988). "Having demonstrated that SST analogues induced the expression of miR-7 and miR-148a and that both these miRNAs are expressed in NETs, we examined how these miRNAs would affect the growth of both the NCI-H727 and CNDT2 carcinoid cell lines by either over expressing or inhibiting them." (PMID 29973528, 2018).
cognitive deficits (15 papers, 2012 to 2025). "It has been reported that dysfunctional GABAergic transmission contributes to neural hyperexcitability in AD brains and dysfunction of SST+ interneurons and PV+ interneurons is associated with the cognitive deficits in AD." (PMID 35353937, 2022). "It is widely recognized that neuronal loss in the neocortex and hippocampus can be involved in cognitive deficits associated with aging, with the dendrite-targeting SST+ interneurons such as hippocampal O-LM cells being affected the most." (PMID 33173468, 2020). "Therefore, the Cys-HCl-induced motor, olfactory discrimination, and cognitive deficits noticed in the experimental animals could be linked, in part, to their reduced levels of somatostatin." (PMID 39061373, 2024). "It is worth noting that improving levels of DCV cargos (i.e., BDNF and somatostatin) partially recover AD-altered networks, preventing cognitive deficits and favoring Aβ clearance." (PMID 28701919, 2017). "Given the role for SST INs in gating spatial information flow in the hippocampus, this may plausibly explain the reported cognitive impairments in 16p11.2 microdeletion rodent models and affected individuals." (PMID 36658491, 2023). "Therefore, the QR2 pathway in SST interneurons provides a fresh new avenue by which to tackle age-related cognitive deficits, while shedding new light onto the functional machinations of long-term memory formation for novel information." (PMID 34518366, 2021). "Synergistic impairment of multiple neuron types: excitatory pyramidal neurons, PV interneurons and SST interneurons, are likely responsible for the neurological phenotypes of social deficits, repetitive behaviors, cognitive impairments and chronic seizures seen in APC cKO mice." (PMID 30369876, 2018). "Serum somatostatin and neuron-specific enolase (NSE) have also been proposed as biochemical markers of early VD: decreased somatostatin levels and increased NSE correlate with cognitive deficits." (PMID 41516246, 2025).
type 2 diabetes (15 papers, 2012 to 2025). "In the present study, we found indications that altered mitochondrial function is linked to alpha cell heterogeneity in type 2 diabetes and that transcriptional delta cell heterogeneity associates with changes in somatostatin secretion." (PMID 39508880, 2025). "Together, these results indicate that type 2 diabetes is associated with reduced somatostatin secretion at 3 mM glucose, perhaps because of a reduced number of δ‐cells, but an increased response to high glucose and depolarization." (PMID 39803760, 2025). "Type 2 diabetes is associated with hypersecretion of somatostatin, which has implications for paracrine regulation of insulin and glucagon secretion." (PMID 39803760, 2025). "Importantly, α-cells of T2D are resistant to inhibition by insulin and somatostatin, which might underlie the hyperglucagonemia in type-2 diabetes." (PMID 32312960, 2020). "Previous studies of somatostatin secretion in type 2 diabetes models have yielded divergent results." (PMID 39803760, 2025). "A similar level of insulin-immunoreactive cells, also containing either glucagon or somatostatin, has been reported within human islets and was increased in donors with type 2 diabetes." (PMID 39791735, 2025). "Further, the study gave insights about the changes in the δ-cell number and expression of SST in human islets during type-2 diabetes." (PMID 36834860, 2023). "Here the authors report that secretion of the hormone is controlled by paracrine inhibition, and that resistance of α-cells to somatostatin can explain hyperglucagonemia in type-2 diabetes." (PMID 32312960, 2020). "In conclusion, GK rats develop a type 2 diabetes with a pronounced either primary or secondary hyperplasia of somatostatin-positive delta cells." (PMID 26236746, 2015). "Similarly, high expression of SST upregulated the renin angiotensin system, maturity-onset diabetes of the young, and primary immunodeficiency, while downregulating taurine and hypotaurine metabolism, glycosaminoglycan biosynthesis, heparan sulfate, and mismatch repair." (PMID 41009659, 2025). "Somatostatin secretion has also been shown to be reduced in both diabetic ob/ob and high fat diet-fed mice, and a recent study showed reduced numbers of ghrelin-secreting cells and reduced circulating levels of ghrelin in human type-2 diabetes, which may explain the impaired somatostatin release." (PMID 39939781, 2025). "This study aimed to investigate the relationship between levels of the stable somatostatin precursor, N-terminal prosomatostatin (NT-proSST), with mortality in type 2 diabetes (T2DM) patients." (PMID 25880900, 2015). "Pancreatic δ-cell-released somatostatin is perceived by its receptor SSTR3 expressed on cilia of nearby β-cells, a process that is disrupted in type-2 diabetes." (PMID 39939781, 2025).